UMODL1 (uromodulin like 1)
Tractability: Antibody: UniProt places it where antibodies can reach, with high confidence; UniProt predicts a signal peptide or a membrane-spanning region; its Gene Ontology location is reachable by antibodies, with medium confidence.
Gene: Protein-coding gene on chromosome 21 (42,062,959 to 42,143,453, forward strand). Ensembl gene ENSG00000177398.
Subcellular location: Cell membrane; Cytoplasm (Isoform 3); Cytoplasm (Isoform 4)
Gene Ontology:
Molecular function: calcium ion binding; peptidase inhibitor activity
Cellular component: cell surface; cytoplasm; external side of plasma membrane; extracellular region; plasma membrane
Genetic constraint (gnomAD): Loss-of-function variants: 117 observed, 126.65 expected, observed/expected ratio (o/e) 0.92, 90% interval 0.79 to 1.08. The upper end of that interval is the gene's LOEUF score, 1.08, which puts it in group 4 of 6, group 1 being the genes least tolerant of losing a copy. Missense variants: 1,637 observed, 1,667 expected, observed/expected ratio (o/e) 0.98, 90% interval 0.94 to 1.02. Synonymous variants: 681 observed, 704.64 expected, observed/expected ratio (o/e) 0.97, 90% interval 0.91 to 1.03.
Homologues: Orthologues: chimpanzee UMODL1 (97% identical), pig UMODL1 (71% identical), dog UMODL1 (69% identical), rat Umodl1 (64% identical), guinea pig UMODL1 (63% identical), mouse Umodl1 (63% identical), macaque UMODL1 (49% identical), zebrafish umodl1 (21% identical). Paralogues in human: UMOD (10% identical), GP2 (7% identical), OIT3 (7% identical), ZPLD1 (6% identical), TECTB (5% identical).
Diseases named in the same sentence as UMODL1 in open-access papers:
UMODL1 is named in the same sentence as 15 diseases in open-access papers, as found by Europe PMC text mining. Sharing a sentence is not in itself a finding about the gene and the disease. The quoted sentences say what the papers report.
myopia (4 papers, 2009 to 2019). "In conclusion, we systematically investigated the common polymorphisms of the UMODL1 gene for association with high myopia by genotyping 59 SNPs in the initial study and 4 SNPs in the follow-up study." (PMID 22857148, 2012). "The uromodulin-like 1 (UMODL1) gene harboring rs2839471 was suggested as a new susceptibility gene for high myopia." (PMID 22857148, 2012). "We suggested that common polymorphisms of the UMODL1 gene were unlikely to play an important role in the genetic susceptibility to high myopia in the Chinese population under study, and the role of UMODL1 in ACD remained to be confirmed." (PMID 22857148, 2012). "The UMODL1 gene was found to be associated with high myopia in Japanese." (PMID 22857148, 2012). "Hence, to date, PAX6, HGF, and UMODL1 remain the strongest candidates for high grade myopia and collagen, type 2, alpha 1 (COL2A1) for common myopia." (PMID 19365569, 2009).
lung adenocarcinoma (2 papers, 2020 to 2024). A carcinoma that arises from the lung and is characterized by the presence of malignant glandular epithelial cells. "Additionally, UMODL1 has been reported to have a presence in lung adenocarcinoma and associated with metastasis." (PMID 39636205, 2024). "Of these genes, PLA2G1B was reported to be associated with smoking-related lung adenocarcinoma, and UMODL1 may drive lung adenocarcinoma metastasis by involving the G-protein coupled receptor protein signaling pathway." (PMID 32484849, 2020).
acute myeloid leukemia (1 paper, 2022). Acute myeloid leukemia (AML) is a group of neoplasms arising from precursor cells committed to the myeloid cell-line differentiation. "UMODL1 expression was low in most cancers, except in acute myeloid leukemia and thymoma." (PMID 35847359, 2022).
autosomal recessive nonsyndromic deafness (1 paper, 2022). "In particular, UMODL1 is located on human chromosome 21 within the Down syndrome’s critical region (autosomal recessive nonsyndromic deafness DFNB10 critical region)." (PMID 35223856, 2022).
Infertility (1 paper, 2022). "Mice overexpressing Umodl1 appear normal at a young age, but they develop premature infertility at the age of six months, possibly by a direct action on ovarian follicles; moreover, it has been reported that the UMODL1 gene product might play a critical role in susceptibility to high myopia." (PMID 35223856, 2022).
lymphoid neoplasm (1 paper, 2016). A neoplasm composed of a lymphocytic cell population which is usually malignant (clonal) by molecular genetic and/or immunophenotypic analysis. "In addition, in the current study, we report for the first time recurrent mutations (5-10%) in CMML in the genes CREBBP, KMT2D and UMODL1, which have been previously reported in lymphoid neoplasms or solid tumors." (PMID 27486981, 2016).
male infertility (1 paper, 2025). The inability of the male to effect fertilization of an ovum after a specified period of unprotected intercourse. "While mutations in UMODL1 have been shown to impact ovarian follicle development, granulosa cell apoptosis and female fertility in model organisms, its role in male infertility remains unclear." (PMID 40229599, 2025). "The male infertility-associated variant rs75957543 (MAF of 1.25%, OR 1.67 (1.39–2.01)) is near UMODL1, which encodes the olfactorin protein, expressed along the migratory route of gonadotropin-releasing hormone neurons." (PMID 40229599, 2025).
cancer (2 papers, 2016 to 2022). A tumor composed of atypical neoplastic, often pleomorphic cells that invade other tissues. "Genes such as MAGEA3 and MAGEA6 contributed targets for 7 cancer types each, while genes such as UMODL1, NLRP4, MAGEC2, ANKRD30A, and GPRC6A contributed targets for only 1 cancer type." (PMID 27439771, 2016). "Depending on the CCLE, UMODL1 and OIT3 were low in various cancer cell lines, including COAD cell lines." (PMID 35847359, 2022). "The GEPIA database was used to evaluate UMODL1 and OIT3 expression in human cancer." (PMID 35847359, 2022).
tumor (1 paper, 2022). "“Gene” module analysis showed that UMODL1 expression significantly correlated with tumor purity, B cells, CD8+ T cells, macrophages, neutrophils, and dendritic cells in COAD (P < 0.05)." (PMID 35847359, 2022). "In conclusion, tumor-infiltrating immune cells may affect the clinical consequences of LINC00114/UMODL1 and LINC00114/OIT3 axes in COAD." (PMID 35847359, 2022).
UMODL1 also shares sentences with these, for which no sentence is quoted: Down syndrome (1 paper); female infertility (1); myopathy (1); ovarian insufficiency (1); thymoma (1); trisomy 21 (1).